CFTR (CF transmembrane conductance regulator)
Diseases named in the same sentence as CFTR in open-access papers (continued):
Sharing a sentence is not in itself a finding about the gene and the disease.
cystic fibrosis (continued). "Additionally, a better understanding of the role of USP10 in the endocytic trafficking of CFTR and other ion channels has the potential to identify new targets for drug development in multiple diseases, including cystic fibrosis." (PMID 33277473, 2020). "As exemplified by CFTR, an ABC transporter that functions as a chloride channel, its dominant mutations are now widely used as molecular targets for therapy of patients with cystic fibrosis." (PMID 34541464, 2020). "Infertility caused by obstructive azoospermia is observed in more than 95% of the males with cystic fibrosis, while 60-70% of the patients with CBAVD have mutations on the CFTR gene without manifesting clinical symptoms of cystic fibrosis." (PMID 32293822, 2020). "Cystic fibrosis, affecting predominantly white populations, is an autosomal recessive disease resulting from a defect in the gene encoding for the chloride channel, CFTR (cystic fibrosis transmembrane conductance regulator)." (PMID 32075640, 2020). "Cystic fibrosis, one of the most common lethal autosomal-recessive diseases in the White population, is a multiorgan disease caused by loss of function of the CF transmembrane conductance regulator (CFTR), an anion channel expressed at the apical membrane of secretory epithelia." (PMID 32853178, 2020). "In addition, COL15A1 is a potential marker for portal fibroblasts with a significant role in biliary fibrosis, while CFTR is a well-known gene for cystic fibrosis, a disease with similar symptoms as BA." (PMID 32848883, 2020). "This protein can interact with other enzymatic proteins, such as AMPK, or ion channels, such as CFTR, which may be important in cystic fibrosis, and with graphene oxide, and may adversely affect heart failure." (PMID 32366041, 2020). "They described a small child with CF (cystic fibrosis) who had received two copies of the same chromosome 7 with a CFTR (cystic fibrosis transmembrane conductance regulator) variant from her carrier mother, and no contribution from her non‐carrier father." (PMID 31793236, 2020). "CFTR modulators, which treat the basic defect of cystic fibrosis, are now available for some patients, dependent on their age and specific mutations;5 however, for the foreseeable future, the early treatment of airways infection will remain a core component of cystic fibrosis treatment." (PMID 33007285, 2020). "However, in contrast to patients with cystic fibrosis, which is principally associated with only the ABC transporter CFTR, patients with refractory cancer usually express several ABC transporter-dependent and -independent mechanisms." (PMID 34541464, 2020). "Furthermore, EVs can deliver CFTR protein to cystic fibrosis donor cells and functionally correct the Cl− channel defect in vitro." (PMID 32224868, 2020). "We hypothesize that loss of CFTR function in cystic fibrosis patients influenced plasma S1P levels." (PMID 32183316, 2020). "The variant may promote a hyper-inflammatory state akin to that observed with the cystic fibrosis gene, CFTR ΔF508, featuring defective autophagy, formation of aggresomes, and activation of the NLPR3 inflammasome." (PMID 32164793, 2020). "In fact, cystic fibrosis although classified as a rare disease, is the most common monogenic disorder in people with primarily European origins, leading to an estimate of 1% of the world’s population carrying one defective copy of the CFTR gene." (PMID 32244346, 2020). "Researchers applied CRISPR to precisely corrected CFTR carrying homozygous F508 deletion (F508del) in exon 10 in the induced pluripotent stem cells (iPSC) separated from cystic fibrosis patients 71 and the overall correction efficiency is up to 90% using piggyBac transposase as selection marker." (PMID 32292501, 2020).
cystic fibrosis (continued). "In this work, we aimed to understand this alteration by means of Atomic Force Microscopy and Force Feedback Microscopy investigation of mechanical properties of cystic fibrosis bronchial epithelial (CFBE) cells stably transduced with either wild type (wt-) or F508del-CFTR." (PMID 32326361, 2020). "Interestingly, the combination of miR-101 and miR-494 has shown to markedly suppress cystic fibrosis by blocking cystic fibrosis transmembrane conductance regulator (CFTR) activity." (PMID 32092824, 2020). "Cystic fibrosis is a monogenic disease associated with high mortality and is caused by mutations affecting the CFTR (cystic fibrosis transmembrane conductance regulator also known as ABCC7) protein, a chloride channel in the plasma membrane of epithelial cells." (PMID 31327045, 2020). "Patients affected by cystic fibrosis lack the function of the cystic fibrosis transmembrane conductance regulator (CFTR), which is involved in bile flow and alkalinization, and may develop liver damage due to chronic cholestasis." (PMID 32192118, 2020). "Finally, transepithelial measurements in a new state-of-the-art Ussing chamber demonstrated effectively restored CFTR function in the cystic fibrosis cell line CFBE41o- after transfection with wtCFTR-mRNA, using nanocapsules loaded with capsaicin." (PMID 32962254, 2020). "We used cystic fibrosis bronchial epithelial cells transduced with wt- or F508del-CFTR." (PMID 32326361, 2020). "In the future, it might be interesting to perform transfection experiments and investigate subsequent ion transport via CFTR and ENaC on the cell lines, NuLi (normal lung, University of Iowa) and CuFi (cystic fibrosis, University of Iowa)." (PMID 32260534, 2020). "Cystic fibrosis is a genetic disease caused by mutations in the CF transmembrane conductance regulator (CFTR) gene, resulting in dysfunctional or absent CFTR protein on the apical membrane of epithelial cells." (PMID 32887484, 2020). "Cystic Fibrosis Transmembrane Conductance Regulator (CFTR) modulators are a class of small molecule drugs that improve the activity of the defective CFTR protein in people with cystic fibrosis, resulting in improved pulmonary function, reduction of pulmonary exacerbations, and improved nutrition." (PMID 33103563, 2020). "Avenues for future research could be to combine two potentiators in S1251N mediates patients to see if there is an increase CFTR mediated chloride secretion and thereby a better treatment for Cystic Fibrosis patients." (PMID 32687499, 2020). "Thus, deletions found in the ΔF508 variant of the Cystic Fibrosis transmembrane regulator (CFTR) triggering CF or missense mutations found in the Z variant of Alpha 1-Antitrypsin deficiency (AATD), leading to lung and liver diseases, can accelerate misfolding and/or generate aggregates." (PMID 32098273, 2020). "Recently, a global exercise resulted in the harmonisation of the definition and designation of these infants as Cystic Fibrosis Transmembrane Conductance Regulator (CFTR)-Related Metabolic Syndrome/Cystic Fibrosis Screen Positive, Inconclusive Diagnosis (CRMS/CFSPID)." (PMID 33073032, 2020). "The most common mutation in CFTR (ΔF508) generates a Cl− channel that is not transported to the plasma membrane, leading to cystic fibrosis." (PMID 31600783, 2020). "Cystic fibrosis missense analysis (CYSMA) is a recently developed website dedicated to CFTR missense variants based on integrated in-house bioinformatics tools, which proved efficient to predict the impact of CFTR variants." (PMID 32512765, 2020). "Cystic fibrosis (CF; MIM# 219700) is an autosomal recessive rare disease caused by CF‐causing variants (henceforward mutations) in the cystic fibrosis transmembrane conductance regulator gene (CFTR; MIM#602421)." (PMID 31245908, 2019). "The interaction between SLC9A3 and CFTR modifies the severity of cystic fibrosis." (PMID 30956978, 2019).
cystic fibrosis (continued). "Owing to similarities between chronic bronchitis and the autosomal-recessive disease Cystic Fibrosis, a significant body of research addresses the hypothesis that dysfunctional CF Transmembrane Conductance Regulator (CFTR) is implicated in the pathogenesis of COPD." (PMID 31477092, 2019). "Hence, genetic variants in SLC26A9, impairing the established cross-talk and interaction with CFTR contribute to the severity of respiratory and gastrointestinal symptoms observed in cystic fibrosis (see review El Khouri and Toure, 2014)." (PMID 31681763, 2019). "Moreover, CBZ has been shown to correct the trafficking defect of ΔF508 CFTR (ABCC9), the most prevalent mutation underlying cystic fibrosis." (PMID 31343405, 2019). "Cystic fibrosis is a recessive genetic disease in which defects or deficits in the cystic fibrosis transmembrane conductance regulator (CFTR) protein result in disease phenotypes of the pancreas, sweat glands, and reproductive, respiratory, and digestive systems." (PMID 30992350, 2019). "Interestingly, the association of RNF5 was consistent with its function as a regulator of the CFTR protein and suggested role in cystic fibrosis." (PMID 31746734, 2019). "Cystic fibrosis (CF, OMIM 219700) is caused by mutations in the CFTR (GenBank M28668.1)." (PMID 30600599, 2019). "Cystic fibrosis remains an under-recognized immunodeficiency due to dysfunctional CFTR that leads to the production of dehydrated mucus, impaired immunity, and subsequent acute and chronic bacterial infections that cause progressive structural and functional changes in the respiratory tract." (PMID 30459435, 2018). "Together with the destruction of pancreatic tissue in certain forms of the disease, reduced CFTR-stimulated insulin secretion might contribute to diabetes in some patients with cystic fibrosis." (PMID 29773801, 2018). "Respiratory failure, driven by airways mucus obstruction, chronic inflammation and bacterial infections, is the main cause of mortality and morbidity in people with cystic fibrosis due to defects in the Cl- and HCO3− transport activity of the CF Transmembrane conductance Regulator (CFTR)." (PMID 30618754, 2018). "Sequencing analysis showed no compound heterozygous or homozygous mutations in 39 genes known to cause PCD, nor in CFTR, gene causing cystic fibrosis." (PMID 29444099, 2018). "Similar results have been found in respiratory epithelial cells, where in the presence of CFTR inhibitor or mutant CFTR the water permeability significantly decreased which highlights the significance of this water channel in cystic fibrosis." (PMID 30050452, 2018). "CF is an autosomic recessive disease caused by at least two mutations of a gene encoding a transmembrane chloride channel called Cystic Fibrosis Transmembrane Conductance Regulator (CFTR) involved in regulation of liquid volume and anions on epithelial surfaces." (PMID 30151190, 2018). "Cystic fibrosis is a progressive, multi-organ, life-threating, autosomal recessive disease caused by variants in CFTR gene leading to reduced or no protein function in approximately 70,000 individuals worldwide." (PMID 30444886, 2018). "Cystic fibrosis, or mucoviscidosis, is a lethal autosomal recessive genetic disease that is very common among Caucasians and is characterized by the abnormal production and function of the gene cystic fibrosis transmembrane conductance regulator (CFTR)." (PMID 30427481, 2018). "Cystic fibrosis transmembrane conductance regulator (CFTR)-ΔF508, α-synuclein, and aminoacyl-tRNA synthetase complex-interacting multifunctional protein-2 (AIMP2) are aggregation-prone proteins associated with the development of cystic fibrosis or PD." (PMID 30469013, 2018). "Cystic fibrosis is a chronic, asymptomatic disease related to a change in salt concentration due to a failure in the cystic fibrosis transmembrane conductance regulator (CFTR)." (PMID 30308990, 2018).
cystic fibrosis (continued). "Yet a better understanding of CFTR misfolding is highly desirable for the development of novel therapeutics that treat the cause rather than the symptoms of cystic fibrosis." (PMID 30302398, 2018). "Targeted genetic testing has also been included in newborn screening algorithms for cystic fibrosis, where an elevated immunoreactive trypsinogen measurement is followed by screening for a panel of CFTR (cystic fibrosis transmembrane conductance regulator) mutations." (PMID 29116556, 2018). "Mutations in the cystic fibrosis transmembrane conductance regulator (CFTR) gene cause abnormal ion transport in the epithelium of several tissues, which results in the production of abnormally thick and sticky mucus that blocks the organ, principally the lung, and is responsible for CF pathology." (PMID 29342838, 2018). "We first compared the performance of PAFA, Eigen, CADD, GWAVA, FATHMM-MKL, and DANN on prioritizing coding variants from five well-studied genes (MLL2, CFTR, BRCA1, BRCA2, and TERT) associated with Kabuki syndrome, cystic fibrosis, breast cancer, or aggressive thyroid tumor, respectively." (PMID 29996888, 2018). "The disruption of this protein complex might enhance the CFTR function of patients suffering from cystic fibrosis." (PMID 30463370, 2018). "Notably, cystic fibrosis, an autosomal recessive disease caused by CFTR gene mutation, results in the dehydration of periciliary liquid layer and deteriorates mucus transport in airway, which is associated with the defective host defense and chronic bacterial infection in CF patients." (PMID 28542554, 2017). "Although this sSNP, by itself, does not cause cystic fibrosis, it is prevalent in patients with CFTR-related disorders." (PMID 28510592, 2017). "The same group also demonstrated a 15 % decrease in gentamicin accumulation in mice with defective CFTR, the gene affected in cystic fibrosis, and hypothesised that CFTR may play a role in the pathway of megalin-mediated endocytosis." (PMID 27848094, 2017). "This potentially could be through the use of the FDA approved drug, Lumacaftor (see Chapter “Cystic Fibrosis: a clinical view”), which improves folding and processing of F508del-CFTR to the plasma membrane, as well as Ivacaftor to improve channel activity." (PMID 27714410, 2017). "Cystic Fibrosis is an autosomal recessive non-curable condition caused by mutations in the Cystic Fibrosis Transmembrane Conductance Regulator (CFTR) gene, located on human chromosome 7." (PMID 28514950, 2017). "The pathological features of cystic fibrosis include aberrant accumulation of hyperviscous mucous in the airways, impaired mucociliary clearance, and increased inflammation partly due to the mutation of cystic fibrosis transmembrane conductance regulator (CFTR)." (PMID 28748360, 2017). "Finally, we performed a limited carrier screening assessment, identifying 28 (4.6%) parents as carriers of P/LP variation in HBB (sickle cell anemia MIM:603903), HEXA (Tay-Sachs disease MIM:272800), or CFTR (cystic fibrosis MIM:219700)." (PMID 28554332, 2017). "In conclusion, miR-145-5p targeting for CFTR induction might be considered just one of the activities to be modulated to reach CFTR correction suitable for cystic fibrosis therapy." (PMID 29286300, 2017). "CFTR dysfunctions may develop due to environmental toxins, cigarette smoke, genetic diseases like cystic fibrosis or acquired pathologies like chronic obstructive pulmonary disease (COPD)." (PMID 28825630, 2017). "Ecuador has not established a common CFTR mutations panel for the diagnosis of cystic fibrosis, therefore this study aims to define this panel by sequencing the 27 exons of this gene in Ecuadorian cystic fibrosis patients." (PMID 29178639, 2017). "Genetic study for the evaluation of CFTR gene might be also helpful to evaluate the presence of latent cystic fibrosis." (PMID 27597925, 2016).
cystic fibrosis (continued). "CFTR is well known as anion channel whose malfunction leads to dysregulation of epithelial fluid transport in the lung, pancreas and other organs, resulting in cystic fibrosis." (PMID 27153809, 2016). "In CF, it has been shown that the progression and severity of pulmonary disease do not appear to correlate exclusively with specific mutations in the causative gene cystic fibrosis transmembrane conductance regulator (CFTR) but appear to be largely dependent on other modifier genes." (PMID 27169516, 2016). "Cystic fibrosis is an autosomal recessive disorder that affects the function of many organs (pancreas, lungs, sweat glands) due to the loss of a chloride channel, the cystic fibrosis transmembrane conductance regulator (CFTR), located in the apical membrane of epithelial cells." (PMID 27182737, 2016). "In the context of cystic fibrosis, various cellular disease models have been established in recent years, including organoids based on induced pluripotent stem cell technology that allowed for functional readouts of CFTR activity." (PMID 27526025, 2016). "Wildtype VT (130pM) was found to increase F508del CFTR, the major mutant responsible for cystic fibrosis, the most common ERAD-dependent genetic disease, in transfected (Gb3 expressing) HeLa cells within 2hrs, even though protein synthesis is completely shut down under such conditions." (PMID 27935997, 2016). "Furthermore, preliminary studies presented by Guimbellot and colleagues at the 2014 North American Cystic Fibrosis Conference confirm our results that P. aeruginosa reduces VX-809 stimulated F508del-CFTR Cl secretion." (PMID 26018799, 2015). "Although homozygous or compound heterozygous mutations in the CFTR gene cause cystic fibrosis, there is little evidence to date that the knowledge would be used for anything other than potentially prenatal counseling." (PMID 26023681, 2015). "Although these mutations are in dbSNP, they occur less frequently than the CFTR p.Phe508del mutation (rs121909001; minor allele frequency ~0.015), which is the leading cause of cystic fibrosis." (PMID 25356967, 2015). "Another example is Cystic fibrosis transmembrane conductance regulator (CFTR) gene-deficient mice, which developed gastrointestinal obstruction rather than the pulmonary lesions characteristic of cystic fibrosis in humans." (PMID 26246962, 2015). "The results suggest that identifying and targeting signalling pathways involved in the folding, trafficking, and breakdown of CFTR may prove a promising way to treat cystic fibrosis." (PMID 26701908, 2015). "The conclusion of this study was that ivacaftor as a CFTR potentiator alone is not an effective therapeutic strategy for patients with cystic fibrosis who are homozygous for the Phe508del mutation." (PMID 26403534, 2015). "Importantly, the most common CFTR mutation by far is Phe508del, which is found on at least one chromosome in around 85 % of people with cystic fibrosis, and correcting the function of Phe508del-CFTR is much more challenging." (PMID 26403534, 2015). "Carrier screening for cystic fibrosis involves analysis for common mutations in the CFTR gene from people with no personal history, or family history, of the disease." (PMID 25304080, 2014). "Inhibitors of cystic fibrosis transmembrane conductance regulator (CFTR) have been widely used for characterizing CFTR function in epithelial fluid transport and in diseases such as secretory diarrhea, polycystic kidney disease and cystic fibrosis." (PMID 24714160, 2014). "Small molecule CFTR inhibitors have been widely used in characterizing CFTR functions in epithelial fluid transport and in diseases such as secretory diarrhea, polycystic kidney disease and cystic fibrosis." (PMID 24714160, 2014). "Increased desaturase expression appears to be linked to cystic fibrosis mutations via stimulation of the AMP-activated protein kinase in the absence of functional CFTR protein." (PMID 25216340, 2014).